SPINK1 (serine peptidase inhibitor Kazal type 1)
Description:
Serine protease inhibitor which exhibits anti-trypsin activity. In the pancreas, protects against trypsin-catalyzed premature activation of zymogens (By similarity). In the male reproductive tract, binds to sperm heads where it modulates sperm capacitance by inhibiting calcium uptake and nitrogen oxide (NO) production.
Synonyms: TATI; PSTI; Spink3; PCTT; TCP
Tractability: Antibody: UniProt places it where antibodies can reach, with high confidence; UniProt predicts a signal peptide or a membrane-spanning region; its Gene Ontology location is reachable by antibodies, with medium confidence. PROTAC: its protein half-life has been measured.
Gene: Protein-coding gene on chromosome 5 (147,824,572 to 147,831,671, reverse strand). Ensembl gene ENSG00000164266.
Subcellular location: Secreted
Pathways (Reactome):
Developmental Biology: Developmental Lineage of Pancreatic Acinar Cells
Gene Ontology:
Molecular function: protein binding; endopeptidase inhibitor activity; peptidase inhibitor activity; serine-type endopeptidase inhibitor activity
Cellular component: extracellular exosome; extracellular region
Genetic constraint (gnomAD): Loss-of-function variants: 4 observed, 8.88 expected, observed/expected ratio (o/e) 0.45, 90% interval 0.22 to 1.03. That is too few expected variants to judge how well the gene tolerates losing a copy. Missense variants: 84 observed, 88.43 expected, observed/expected ratio (o/e) 0.95, 90% interval 0.8 to 1.14. Synonymous variants: 36 observed, 33.21 expected, observed/expected ratio (o/e) 1.08, 90% interval 0.83 to 1.43.
Homologues: Orthologues: chimpanzee SPINK1 (99% identical), macaque SPINK1 (94% identical), pig SPINK1 (75% identical), dog SPINK1 (71% identical), mouse Spink1 (70% identical), guinea pig SPINK1 (68% identical), rat Spink1l (67% identical), rabbit SPINK1 (63% identical), rat Spink1 (63% identical).
Diseases named in the same sentence as SPINK1 in open-access papers:
SPINK1 is named in the same sentence as 125 diseases in open-access papers, as found by Europe PMC text mining. Sharing a sentence is not in itself a finding about the gene and the disease. The quoted sentences say what the papers report.
pancreatitis (84 papers, 1986 to 2025). Inflammation of the pancreas. "Gene therapy using adeno-associated viral vector containing the human serine protease inhibitor Kazal type 1 (SPINK1) gene has shown efficacy against murine pancreatitis in preclinical experiments." (PMID 40753100, 2025). "In CF, SPINK1 is often upregulated and, depending on any mutations in the gene, can influence the progression of several diseases, specifically pancreatitis in CF and pancreatic cancer." (PMID 41158431, 2025). "Beyond its role in pancreatic disorders, SPINK1 overexpression is associated with pancreatitis, Prostate cancer (PC), and chemoresistance through activation of the PI3K/Akt and MAPK pathways." (PMID 40872585, 2025). "Around 2% of the general population carries SPINK1 mutations, but less than 1% of those carriers go on to develop pancreatitis." (PMID 39687810, 2024). "Genetic predispositions, such as variants in the SPINK1 gene, have been linked to an increased risk of pancreatitis." (PMID 39564382, 2024). "Genetic analysis revealed a heterozygous SPINK1 c.194 + 2T>C variant (rs148954387), a well-known pathogenic variant associated with increased susceptibility to pancreatitis." (PMID 39564382, 2024). "This study demonstrates that heterozygous loss of SPINK1 in preclinical mouse models promotes pancreatitis onset and progression in a trypsin-dependent manner." (PMID 38768901, 2024). "Mutation in the CASR gene alone or combination with the SPINK1 gene is involved in the cause of pancreatitis or pancreatic cancer." (PMID 36275616, 2022). "The results also strengthen the notion that a decline in inhibitor levels explains pancreatitis risk associated with the large majority of SPINK1 variants." (PMID 33515547, 2021). "Genetic factors including mutations in CFTR, PRSS1, SPINK1 genes play an important role among the causes of acute, recurrent pancreatitis." (PMID 33652736, 2021). "SPINK1 encodes a pancreatic secretory trypsin inhibitor, and mutations interfere with the protective function, and predispose a person to pancreatitis, possibly via increased intrapancreatic trypsin activity." (PMID 33375361, 2020). "Recently, the p.N34S mutation was found in 20% of patients carrying the functionally defective TRPV6 variants, suggesting that the combination of mutated TRPV6 and SPINK1 p.N34S results in predisposition to pancreatitis, as well as the CFTR gene." (PMID 33375361, 2020). "We describe the case of a middle-aged male who presented with recurrent pancreatitis in the setting of the serine peptidase inhibitor, Kazal type 1 (SPINK-1) genetic polymorphism." (PMID 30891392, 2019). "Then we integrated both the in silico splicing prediction procedure and the full-length gene assay into a stepwise approach in order to classify a series of SPINK1 intronic variants newly discovered in Chinese and French pancreatitis patients." (PMID 30755276, 2019). "Pathogenic SPINK1 variants predispose to pancreatitis by lowering the inhibitory capacity of prematurely activated trypsin within the pancreas." (PMID 30755276, 2019). "The second dataset comprised five novel rare proximal intronic variants identified through the routine analysis of the SPINK1 gene in French pancreatitis patients." (PMID 30755276, 2019). "Mutation in the SPINK1 gene leads to trypsin being uninhibited which increases the risk of pancreatitis." (PMID 29515728, 2017). "While up to 2% of the general population carry SPINK1 mutations, the actual number of individuals with SPINK1 associated pancreatitis is extremely rare, with less than 1% of carriers going on to developing pancreatitis." (PMID 29515728, 2017). "SPINK1 encodes a pancreatitis secretory trypsin inhibitor which is released by pancreatic acinar cells when there is inflammation." (PMID 29515728, 2017). "Although the mechanism of the SPINK1 N34S to pancreatitis is unclear, it was thought that the mutation leads to a diminished capacity to inhibit trypsin." (PMID 29333155, 2017).
pancreatitis (continued). "In the present study, the frequency of SPINK1 mutations in 221 patients with pancreatitis was 6.3 %, which was significantly higher than in the control group (P = 0.03)." (PMID 26100556, 2015). "SPINK1 polymorphisms are common in the general population (~2 %) and are significantly associated with pancreatitis." (PMID 26100556, 2015). "Serine protease inhibitor Kazal type 1 (SPINK1) 194+2T>C mutation is most frequently observed in Chinese pancreatitis patients and influences the clinical course of idiopathic chronic pancreatitis patients." (PMID 26632706, 2015). "When the family history was included in the regression models, the contribution of SPINK1-CTRC combination to the risk of hospitalization for pancreatitis or abdominal pain remained significant (p = 0.032)." (PMID 24795752, 2014). "We have then evaluated the association of this CTRC (rs545634) and SPINK1 (rs11319) combination with recurrent pancreatitis in logistic regression analysis, including age, gender and smoking status as covariates." (PMID 24795752, 2014). "Only SPINK1 N34S heterozygotes were used for trans-heterozygote analysis with CFTR, since homozygous SPINK1 N34S is sufficient to cause pancreatitis." (PMID 25033378, 2014). "In summary, SPINK1 is described as an inhibitor of the onset of pancreatitis, and the mutation of SPINK1 is able to lower the threshold for pancreatitis from other genetic or environmental factors." (PMID 24932227, 2014). "Genetic mutations, such as those affecting the SPINK1 gene, may predispose individuals to pancreatitis by reducing the threshold for pancreatic inflammation, especially when other triggers are present." (PMID 40605893, 2025). "Therefore, we cannot exclude the possibility of undetected second CFTR variants, modifier alleles, or other pancreatitis‐associated gene variants (i.e., SPINK1, PRSS1, or CTRC)." (PMID 40468859, 2025). "Thus, SPINK1 mutations not only predispose recipients to pancreatitis but also cause pancreatic carcinogenesis, emphasising its importance in diagnostics and cancer prevention." (PMID 40872585, 2025). "Nevertheless, given that SPINK1 c.194 + 2T>C variant increases susceptibility to pancreatitis, the patient's mother has been advised to maintain a healthy lifestyle and to seek medical attention if any symptoms associated with pancreatitis develop." (PMID 39564382, 2024). "For example, oxidative stress from alcohol and smoking may exacerbate genetic mutations associated with pancreatitis, such as those in the SPINK1 and CFTR genes." (PMID 39221257, 2024). "PSTI/SPINK1 gene expression is associated with the onset of pancreatitis." (PMID 37242166, 2023). "The associating between SPINK1 mutation and pancreatitis has been well established." (PMID 36555366, 2022). "Mutation of CASR gene alone or in combination with SPINK1 gene mutation can lead to pancreatitis." (PMID 36275616, 2022). "Mutation in SPINK1 N34S is an accepted risk factor for pancreatitis." (PMID 36555366, 2022). "Additionally, we discuss the mechanism behind SPINK-1 polymorphisms in the development of pancreatitis as well as the role of genetic screening for the polymorphism in the general population." (PMID 30891392, 2019). "While mutations in the PRSS1 cause chronic pancreatitis on their own, the SPINK1 mutation is instead likely to act as a disease modifier, lowering the threshold for an individual developing pancreatitis from other genetic factors such as the CFTR mutations and environmental factors." (PMID 29515728, 2017). "Mutations in the SPINK1 gene lead to premature trypsinogen activation and resultant pancreatitis." (PMID 29515728, 2017). "Thus, our observations and those of other researchers suggest that SPINK1 mutations predispose to severe pancreatitis." (PMID 26100556, 2015).
pancreatitis (continued). "It is possible that mutations in CTRC and SPINK1 genes contribute to this process and further increase the pancreatitis risk conferred by LPLD by either increasing the level of activated proteases, blocking active site of trypsin or decreasing proteases degradation." (PMID 24795752, 2014). "Mutations in SPINK1 (Spink3 in mice) have been genetically linked to pancreatitis in humans." (PMID 24699552, 2014). "Indeed, mutant variants in CTRC and SPINK1 genes are known to contribute to pancreatitis susceptibility." (PMID 24795752, 2014). "SPINK1 mutations in patients with pancreatitis are firmly demonstrated in numerous studies." (PMID 24932227, 2014). "The N34S mutation in serine protease inhibitor Kazal type 1 (SPINK 1) gene may downregulate the threshold for the development of pancreatitis." (PMID 22934106, 2012). "For example, most of the known gene mutations linked to pancreatitis, such as the serine protease inhibitor Kazal-type 1 (SPINK1) and cystic fibrosis transmembrane conductance regulator (CFTR), increase the likelihood of developing the disease, but do not appear to initiate it by themselves." (PMID 23185258, 2012). "However, like other pathogenic variants of pancreatitis, the SPINK1 c.194 + 2T>C variant is also found in healthy individuals, suggesting that additional factors such as other genetic variants or lifestyle influences likely play a significant role in disease expression." (PMID 39564382, 2024). "Therefore, systematic inhibition of SPINK1 might increase the risk of potential adverse side effects, particularly pancreatitis." (PMID 34747365, 2021). "SPINK1 protects the pancreas from the impact of prematurely activated trypsinogen, and SPINK1 mutations, particularly the N34S mutation, have also been reported to lower the threshold for pancreatitis from other genetic or environmental factors instead of initiating the development of CP." (PMID 24932227, 2014). "However, co-inheritance of the TCF7L2 variants with the pancreatitis associated susceptibility variants in SPINK1 and CTSB genes may predict the development of diabetes in these patients, but these observations need to be confirmed independently." (PMID 18706099, 2008). "Among them, SPINK1 is the most well-studied part, extensively recognised for its role in pancreatitis, cancer, and sepsis, where it controls trypsin activity and promotes tumor growth via PI3K/Akt and MAPK pathways." (PMID 40872585, 2025). "The observations will facilitate the development of advanced viral vectors harboring mouse Spink1 for preclinical therapeutic studies in mouse models of pancreatitis." (PMID 40753100, 2025). "Another defense strategy of the pancreas against trypsinogen autoactivation is the enzyme SPINK1, which inactivates prematurely activated trypsin and protects against pancreatitis." (PMID 40427173, 2025). "Understanding the role of SPINK1 is critical for maintaining pancreatic health and avoiding pancreatitis." (PMID 40872585, 2025). "The findings will facilitate the development of improved viral vectors harboring mouse Spink1 for therapeutic trypsin inhibition in mouse models of pancreatitis." (PMID 40753100, 2025). "A direct comparison with the present study is difficult due to the different experimental conditions employed, but the overall efficacy of virally transduced SPINK1 against pancreatitis is consistent with our conclusions." (PMID 38768901, 2024). "Individuals who underwent germline multigene testing for pancreatitis susceptibility genes (CASR, CFTR, CPA1, CTRC, PRSS1, SPINK1) through a large commercial laboratory between 2017 and 2022 were included." (PMID 39172977, 2024). "Next Generation Sequencing was performed to analyze a panel of nine genes associated with pancreatitis (CaSR, CFTR, CPA1, CTRC, CTSB, KRT8, PRSS1, PRSS2, and SPINK1)." (PMID 38927485, 2024).
pancreatitis (continued). "In fact, the SPINK1 c.194 + 2T>C variant (rs148954387), also known as IVS3 + 2T>C, is one of the most common genetic variants associated with pancreatitis, particularly in East-Asian populations." (PMID 39564382, 2024). "We investigated the expression of pancreatitis-associated genes with the ability to act as positive regulators of the IL-6 amplifier; these genes include GGT1, PRSS1, CASR, CTRB1, ABO, SPINK1, and CTRC." (PMID 38806529, 2024). "PRSS1, serine peptidase inhibitor Kazal type 1 and chymotrypsin C are specifically or highly expressed in the acinar cells of a patient with pancreatitis." (PMID 37682188, 2023). "They include DNA damage response and DNA repair genes (ATM, BRCA1, BRCA2, and POLQ), pancreatitis gene (SPINK1) and cell apoptosis gene (CASP8)." (PMID 37234870, 2023). "The human serine protease inhibitor, Kazal type 1 (SPINK1), plays a critical role in inhibiting intrapancreatic trypsinogen activation and is considered a key mechanism in preventing the development of pancreatitis." (PMID 37500741, 2023). "At least five genes have been identified to be associated with pancreatitis: serine protease 1 (PRSS1), serine peptidase inhibitor Kazal type 1 (SPINK1), CFTR, chymotrypsin C (CTRC), and calcium sensing receptor (CASR)." (PMID 35844741, 2022). "SPINK1 is an antiprotease which serves as an inactivator of prematurely activated trypsin and therefore protects against pancreatitis." (PMID 36555366, 2022). "Mutations in PRSS1, SPINK1, CTRC, CASR, and CFTR were linked with pancreatitis and pancreatic cancers when the molecular basis of pancreatitis was investigated." (PMID 36434531, 2022). "The genetic factors leading to pancreatitis have been studied extensively and several genes such as SPINK1, CFTR, HLA‐DRB*0401, and PRSS1 have been attributed with the increase in predisposition to develop pancreatitis." (PMID 35340657, 2022). "Consistent with this notion, mice and humans with homozygous deletion of the SPINK1 gene develop severe and early onset pancreatitis that results in trypsin-dependent destruction of the pancreas." (PMID 33515547, 2021). "Loss-of-function mutations in serine protease inhibitor Kazal-type 1 (SPINK1), which can inactivate intrapancreatic trypsin activity, are associated with pancreatitis risk." (PMID 34436220, 2021). "SPINK1 is known for its roles in inhibiting pancreatic trypsin in cases of premature trypsinogen activation and in familial forms of pancreatitis." (PMID 34861815, 2021). "The serine protease inhibitor Kazal type 1 (SPINK1) protects the pancreas from intrapancreatic trypsin activation that can lead to pancreatitis." (PMID 33515547, 2021). "Germline testing, currently for recommended etiologic mutations associated with pancreatitis, includes evaluation for pathogenic variants in the CEL, CFTR, CPA1, CTRC, PRSS1, and SPINK1 genes in symptomatic individuals." (PMID 33375361, 2020). "SPINK1 N34S (rs17107315), an A>G transition in exon 3, has previously been shown to correlate with chronic, idiopathic, and recurrent pancreatitis." (PMID 29333155, 2017). "These mice develop spontaneous pancreatitis, revealing a critical role of SPINK1 in regulating normal autophagy in the exocrine pancreas." (PMID 27845447, 2016). "This notion is also supported by the genetic evidence that mutations in cationic trypsinogen (PRSS1), pancreatic secretory trypsin inhibitor (SPINK1), and chymotrypsinogen C (CTRC) are associated with the susceptibility of pancreatitis." (PMID 25140315, 2014). "More laboratorial and clinical studies are required to support the role of SPINK1 between pancreatitis and PC." (PMID 24932227, 2014). "In all models, a positive family history of pancreatitis was a significant predictor of recurrent hospitalizations independently of the contribution of SPINK1 or CTRC (p < 0.001)." (PMID 24795752, 2014).